USP25 (ubiquitin specific peptidase 25)
Diseases named in the same sentence as USP25 in open-access papers (continued):
Sharing a sentence is not in itself a finding about the gene and the disease.
glioma (3 papers, 2022 to 2025). A benign or malignant brain and spinal cord tumor that arises from glial cells (astrocytes, oligodendrocytes, ependymal cells). "Our findings demonstrate that USP25 promotes glioma proliferation by stabilizing METTL3 in the cytoplasm, thereby enhancing EGFR translation." (PMID 41321637, 2025). "The analysis of clinical glioma samples reveals a positive correlation between USP25 and METTL3 protein levels, with both significantly upregulated in high-grade glioma." (PMID 41321637, 2025). "The protein levels of both METTL3 and USP25 were higher in high-grade gliomas (WHO Grades III and IV) compared to low-grade gliomas and non-tumor brain samples." (PMID 41321637, 2025). "This list of genes includes three DUBs (USP14, USP19, USP25) shared with the list of differentially expressed ERAD genes in glioma." (PMID 37892185, 2023). "The USP25-overexpressed and USP25-knockdown glioma cells were established on U251 and U87 cells, respectively." (PMID 35450028, 2022). "The role of USP25-mediated ubiquitination of TNKS1 in regulating the Wnt pathway in glioma cells was further verified." (PMID 35450028, 2022). "Glioma cell invasion, migration, and proliferation activity were dramatically inhibited in USP25-knockdown glioma cells and promoted in USP25-overexpressed glioma cells." (PMID 35450028, 2022). "All in all, the data gained revealed that USP25 facilitated glioma cell invasion, migration, and proliferation by Wnt/β-catenin regulation through the deubiquitination on TNKS1." (PMID 35450028, 2022). "Findings gained collectively proposed that proliferation of glioma cells was significantly facilitated by USP25." (PMID 35450028, 2022). "USP25 facilitated glioma cell invasion, migration, and proliferation by regulating Wnt/β-catenin through the deubiquitination on TNKS1." (PMID 35450028, 2022). "In the current study, P-β-catenin, Cyclin D1, β-catenin, and C-myc levels expressed in the Wnt pathway were positively regulated by USP25 in U251 and U87 glioma cells." (PMID 35450028, 2022). "In contrast, this study provides a direct research basis for USP25 as a therapeutic target in glioma and its mechanism with TNKS1, and USP25 will become another significant discovery in glioma treatment." (PMID 35450028, 2022). "TNKS1 expression levels were found to be considerably repressed in USP25-knockdown glioma cells and elevated in USP25-overexpressed glioma cells, accompanied by Wnt/β-catenin pathway key protein downregulation and upregulation, respectively." (PMID 35450028, 2022). "Among the three siRNAs, USP25 expression in glioma cells transfected with siRNA-2 was the lowest." (PMID 35450028, 2022). "This outcome indicates that USP25 activates the Wnt/β-catenin pathway in glioma cells." (PMID 35450028, 2022). "Therefore, we suspected that USP25 impacts glioma cell development and growth by Wnt/β-catenin signaling pathway regulation via mediating TNKS1 ubiquitination." (PMID 35450028, 2022). "Therefore, siRNA-2 was chosen to knockdown USP25 in glioma cells in the subsequent experiments." (PMID 35450028, 2022). "To investigate the correlation between METTL3 and USP25, we analyzed the protein levels of USP25 and METTL3 in a broad panel of cancer cell lines and 37 clinical glioma samples, along with 11 brain tissues from patients with non-tumor." (PMID 41321637, 2025). "Employing the R2 genomics platform to query the 99 DUBs for their association with the GO category of Regulation of the ERAD pathway, we identified 3 DUB genes in this category as differentially expressed in the glioma dataset: USP14, USP19, and USP25." (PMID 37892185, 2023). "TNKS1 ubiquitination level was knowingly increased in USP25-knockdown glioma cells and reduced in USP25-overexpressed glioma cells, suggesting TNKS1 ubiquitination levels were negatively regulated by USP25." (PMID 35450028, 2022). "Moreover, USP25 enhances EGFR expression through cytosolic METTL3, driving glioma progression." (PMID 41321637, 2025).
glioma (continued). "To date, no therapeutic role has been found regarding USP25 in glioma." (PMID 35450028, 2022). "Therefore, in the present study, we investigated the effect of USP25 on the level of ubiquitination of TNKS1 and on the function and mechanism of glioma cell proliferation, invasion, and migration by interfering with the expression of USP25 in human glioma cells U87 and U251." (PMID 35450028, 2022).
influenza (3 papers, 2023 to 2024). An acute viral infection of the respiratory tract, occurring in isolated cases, in epidemics, or in pandemics; it is caused by serologically different strains of viruses (influenzaviruses) designated A, B, and C, has a 3-day incubation period, and usually lasts for 3 to 10 days. "Here, we identify a critical role of Usp25 in metabolic reprogramming upon challenge with influenza and SARS-CoV-2." (PMID 37683630, 2023). "To determine how Usp25-Erlin1/2 restricted influenza infection, we first generated shRNA-mediated depletions of Erlin1, Erlin2, and a combination of Erlin1/2." (PMID 37683630, 2023).
Insulin resistance (3 papers, 2021 to 2026). Increased resistance towards insulin, that is, diminished effectiveness of insulin in reducing blood glucose levels. "Ubiquitin-specific peptidase 25 (USP25) in adipocytes has been proven to be involved in insulin resistance, a noteworthy characteristic of NAFLD." (PMID 39395794, 2024). "Insulin resistance and hyperandrogenemia, major complications of PCOS, were both alleviated in the USP25-deficient mice with PCOS, indicating the promise of USP25 in the diagnosis and treatment of PCOS in the future." (PMID 34805185, 2021). "In terms of the metabolic condition, GTT and ITT results, as well as HOMA-IR levels in mice, all revealed that the deletion of USP25 alleviated the symptoms of insulin resistance in the animals with PCOS." (PMID 34805185, 2021). "Usp25-KO mice showed restrained adipose tissue development and improved insulin resistance, whereas USP25-deficient preadipocytes failed to differentiate." (PMID 41692245, 2026).
pancreatic ductal adenocarcinoma (3 papers, 2022 to 2025). An infiltrating adenocarcinoma that arises from the epithelial cells of the pancreas. "USP25 represents an exciting therapeutic target and should be considered as a potential therapy for human pancreatic ductal adenocarcinoma." (PMID 35440539, 2022). "However, in the extremely hypoxic tumor microenvironment of pancreatic ductal adenocarcinoma, USP25 still deubiquitinate HIF-1α to abrogate its degradation." (PMID 36998063, 2023). "Given that the mechanism of USP25 antagonism under this hypoxic condition was not described, whether there are other E3 ligases targeting HIF-1α that can be antagonized by USP25 in pancreatic ductal carcinoma deserves further investigation." (PMID 36998063, 2023).
Down syndrome (2 papers, 2022 to 2024). "In particular, a L1M5 element is located within the intron of the USP25 gene on Chromosome 21, whose trisomy is associated to Down syndrome (DS; trisomy-21), a condition associated to a high AD risk." (PMID 35585302, 2022). "Although there have been reports on the up-regulation of USP25 expression levels following RNA and DNA virus infections, LPS treatment, and in Down syndrome patients, the precise regulation of USP25 protein remains unclear." (PMID 38616174, 2024).
experimental autoimmune encephalomyelitis (2 papers, 2023 to 2024). An autoimmune demyelinating disease of the central nervous system that is produced experimentally in animals by the injection of homogenized brain or spinal cord in Freund's adjuvant. "In a study comparing wild-type and USP25-deficient mice, the induction of experimental autoimmune encephalomyelitis (EAE) revealed a significant exacerbation of EAE pathology in USP25−/− mice." (PMID 38616174, 2024). "In the context of experimental autoimmune encephalomyelitis (EAE), a mouse model of multiple sclerosis, USP25-deficient mice display more severe EAE pathology compared to wild-type mice." (PMID 38616174, 2024).
glioblastoma (2 papers, 2023 to 2025). The most malignant astrocytic tumor (WHO grade IV). "METTL3 was detected in both the cytoplasm and nucleus of glioblastoma cell lines U87-MG, U251, A172, and U373, whereas USP25 was almost exclusively detected in the cytoplasm." (PMID 41321637, 2025).
intestinal cancer (2 papers, 2021 to 2024). "Furthermore, inhibition of USP25 by AZ1 in a mouse model was shown to suppress inflammation linked to bacterial infections in the intestine and enhance the immune response while inhibiting the activity of USP25 in promoting intestinal cancer." (PMID 38816515, 2024).
leukemia (2 papers, 2021 to 2023). A malignant (clonal) hematologic disorder, involving hematopoietic stem cells and characterized by the presence of primitive or atypical myeloid or lymphoid cells in the bone marrow and the blood. "The depletion of USP25 mediated by shRNA increases ubiquitinated BCR-ABL, which can promote the degradation of BCR-ABL protein in Philadelphia (Ph)-positive leukemia cells." (PMID 34249948, 2021).
Miscarriage (2 papers, 2022 to 2024). A pregnancy that ends at a stage in which the fetus is incapable of surviving on its own, defined as the spontaneous loss of a fetus before the 22th week of pregnancy. "Correspondingly, evidence from in vitro studies indicates that RNA metabolism is also involved in the occurrence of miscarriage, for example, miR-27a-3p induced degradation of USP25 inhibits the invasive ability of trophoblast cells." (PMID 35370464, 2022). "Interestingly, the expression of miR-27a-3p was negatively related to ubiquitin-specific protease 25 (USP25) in recurrent miscarriage patients." (PMID 38666946, 2024).
Obesity (2 papers, 2012 to 2026). Accumulation of substantial excess body fat. "In this study, we aimed to explore how the expression of USP25 contributes to obesity induced by a high-fat diet (HFD)." (PMID 41692245, 2026).
synucleinopathy (2 papers, 2020 to 2024). A neurodegenerative disease that is characterized by the abnormal accumulation of aggregates of alpha-synuclein protein in neurons, nerve fibers or glial cells. "Notably, PD is a well-known synucleinopathy; USP25 was previously implicated in a GWAS PD study, however this finding was not further replicated." (PMID 38201415, 2024). "More specifically, homozygous carriers of the USP25 rs2823357 polymorphsim progressed to synucleinopathies faster than others." (PMID 38201415, 2024).
amyloid (1 paper, 2022). "In summary, our findings revealed that DS-related USP25 plays a role in AD-related amyloid pathology by modulating APP processing and degradation, providing a potential pharmacologic target for treating AD, especially in patients with DS." (PMID 35229730, 2022). "Increased USP25 gene dosage aggravates amyloid pathology in AD mice." (PMID 35229730, 2022). "However, it is still unknown whether and how triplication of USP25 in the DS brain contributes to AD-like neuropathological features, such as amyloid deposition." (PMID 35229730, 2022).
cervical cancer (1 paper, 2025). A primary or metastatic malignant neoplasm involving the cervix. "To verify USP25 influences KIFC1 stability by mediating its deubiquitination, we assessed the interaction between KIFC1 protein and ubiquitin in cervical cancer (CCa) cells." (PMID 40379626, 2025). "Collectively, our findings elucidate the previously unknown functions and mechanisms of the USP25/KIFC1/MYCBP signaling axis in CCa progression, underscoring KIFC1 as a promising therapeutic target for cervical cancer." (PMID 40379626, 2025). "To explore whether USP25 facilitates the progression of cervical cancer (CCa) through modulating KIFC1, we investigated the effects of KIFC1 overexpression in CCa cells with suppressed USP25 expression." (PMID 40379626, 2025). "The USP25/KIFC1/MYCBP signal axis detected by RT-PCR did not change the expression level of c-MYC mRNA, but affected the expression levels of c-MYC transcription targets CDK4, CDK2, cyclin D1 and cyclin E which these have been reported to be regulated by c-MYC transcription in cervical cancer." (PMID 40379626, 2025).
cyst (1 paper, 2021). A sac-like closed membranous structure that may be empty or contain fluid or amorphous material. "When comparing the two DHEA-treated groups, the ovaries of the USP25+/+ DHEA group had a cyst-like appearance, considerably thinner follicular walls, and fewer granulosa cell layers than those of the DHEA-treated USP25–/– mice." (PMID 34805185, 2021).
diabetes (1 paper, 2024). "The results showed that intravitreal injection of AAV-sh-USP25 alleviated diabetes-induced retinal inflammation 8 weeks after STZ injection, as evidenced by reduced expression levels of Iba-1, MCP-1, IL-1β, and TNF-α." (PMID 38436811, 2024). "Subsequently, we conducted a detailed investigation of the upregulation of USP25 expression in the retinas of mice with STZ-induced diabetes for 6 weeks using raw matrix data." (PMID 38436811, 2024). "We next investigated whether USP25 regulates the diabetes-induced inflammation in the retina in vivo." (PMID 38436811, 2024). "As the duration of diabetes increased, USP25 expression gradually elevated, peaking at 12 weeks of STZ-induced DM." (PMID 38436811, 2024).
diabetic nephropathy (1 paper, 2024). "In addition, elevated USP25 expression promotes inflammation and fibrosis in diabetic nephropathy." (PMID 38436811, 2024).
diabetic retinopathy (1 paper, 2024). "In conclusion, the promotion of diabetic retinopathy (DR) progression by USP25 is attributed to its facilitation of microglial activation induced by high glucose levels, a process mediated by the ROCK pathway." (PMID 38436811, 2024).
glomerulonephritis (1 paper, 2024). A renal disorder characterized by damage in the glomeruli. "To further investigate the association between USP25 expression and glomerulonephritis, we examined USP25 levels in Faslpr mice, which exhibit autoimmune abnormalities resembling human systemic lupus erythematosus." (PMID 38616174, 2024). "USP25-deficient mice exhibited more severe glomerulonephritis pathology compared to wild-type mice." (PMID 38616174, 2024). "Such insights could lead to new therapeutic strategies for targeting USP25 in inflammatory diseases like glomerulonephritis." (PMID 38616174, 2024).
head and neck squamous cell carcinoma (1 paper, 2025). A squamous cell carcinoma that arises from any of the following anatomic sites: lip and oral cavity, nasal cavity, paranasal sinuses, pharynx, larynx, and salivary glands. "Here, we sought to identify the mechanisms of USP25 modulation in the TIME of head and neck squamous cell carcinoma (HNSCC)." (PMID 41326342, 2025).
heart failure (1 paper, 2025). Inability of the heart to pump blood at an adequate rate to meet tissue metabolic requirements. "We therefore assessed whether USP25 deficiency could aggravate chronic I/R injury (30 min ischaemia followed by 2‐week reperfusion) and concomitant heart failure." (PMID 39985261, 2025).
Hepatic steatosis (1 paper, 2024). Steatosis is a term used to denote lipid accumulation within hepatocytes. "Indeed, our results indicated that USP25 impaired the K48-linked ubiquitination and degradation of PPARα and that resupplying PPARα in USP25-deficient mice ameliorated diet-induced hepatic steatosis." (PMID 39395794, 2024). "We also found that Usp25 knockout mice presented much more severe hepatic steatosis when they were fed a high-fat diet." (PMID 39395794, 2024). "However, the effects of Usp25 on hepatic steatosis were replicated in primary hepatocytes and liver cell lines." (PMID 39395794, 2024). "More importantly, a USP25 inhibitor also exacerbated diet-induced hepatic steatosis in mice, which could unveil novel therapeutic targets and strategies for managing this increasingly prevalent liver disease." (PMID 39395794, 2024). "Additionally, we observed a correlation between USP25 and PPARα protein levels, indicating the potential role of USP25 in modulating PPARα expression in hepatic steatosis." (PMID 39395794, 2024). "Additionally, we found that a USP25 inhibitor could exacerbate diet-induced hepatic steatosis." (PMID 39395794, 2024). "More importantly, the deletion of USP25 exacerbated hepatic steatosis in a diet-induced NAFLD mouse model and in FFA-induced cell steatosis, which indicated that USP25 participated in NAFLD progression." (PMID 39395794, 2024). "In contrast, treatment with a Pparα agonist in HFD-fed USP25 KO mice did not alleviate metabolic phenotypes or hepatic steatosis, as confirmed by histological analysis, likely due to decreased Pparα levels." (PMID 39395794, 2024).
Hyperglycemia (1 paper, 2024). An increased concentration of glucose in the blood. "Our study presents the novel finding that the USP25/ROCK axis modulates the hyperglycemia-mediated microglial inflammatory response, both in vivo and in vitro." (PMID 38436811, 2024).
idiopathic pulmonary fibrosis (1 paper, 2025). Idiopathic pulmonary fibrosis (IPF) is a nonneoplastic pulmonary disease that is characterized by the formation of scar tissue within the lungs in the absence of any known cause. "Besides, we examined the expression of USP25 and macrophages (marked CD68) in fibrotic lungs of idiopathic pulmonary fibrosis (IPF) patients, and immunofluorescence showed that USP25 was highly expressed in fibrotic tissues and co-localized mainly with macrophages." (PMID 39781451, 2025).
inflammatory bowel disease (1 paper, 2025). A spectrum of small and large bowel inflammatory diseases of unknown etiology. "A genome-wide association study, which identified African-specific susceptibility loci in African Americans with inflammatory bowel disease, showed that USP25 is closely related to the pathogenesis of IBD." (PMID 39773987, 2025).
ischaemic cardiomyopathy (1 paper, 2025). "We also confirmed that the mRNA level of USP25 in the myocardial tissue of patients with ischaemic cardiomyopathy was significantly lower than that in patients with non‐ischaemic cardiomyopathy." (PMID 39985261, 2025).